TCF7L2 (transcription factor 7 like 2)
Diseases named in the same sentence as TCF7L2 in open-access papers (continued):
Sharing a sentence is not in itself a finding about the gene and the disease.
breast cancer (continued). "We investigated the effect of the TCF7L2 rs12255372 variant on familial breast cancer (BC) risk by means of TaqMan allelic discrimination, analyzing BRCA1/2 mutation-negative index patients of 592 German BC families and 735 control individuals." (PMID 17109766, 2006). "We hypothesis that the distribution of alleles, genotypes, and haplotypes of the rs1133683 and rs2240308 variants of the AXIN2, and the rs7903146 and rs12255372 variants of the TCF7L2, are linked to major clinicopathological characteristics of breast cancer." (PMID 35996498, 2022). "This study tests the hypothesis of links between AXIN2 rs1133683 and rs2240308, and TCF7L2 rs7903146 and rs12255372 variants in breast cancer." (PMID 35996498, 2022). "Association of TCF7L2 genotypes with clinical characteristics of breast cancer." (PMID 35996498, 2022). "TCF7L2 variants have been found to be associated with breast cancer incidence." (PMID 35992833, 2022). "Likewise, patients carrying the homozygous T/T genotype of the TCF7L2 rs12255372 variant showed a significant association with breast cancer and with the possibility of reach the advanced TNM stages III + IV." (PMID 35996498, 2022). "The LUCAT1/miR-5582-3p/TCF7L2 axis will provide insights in the mechanisms of stemness regulation and provide theoretical support for finding new diagnostic markers and specific therapeutic targets for breast cancer." (PMID 31300015, 2019). "The LUCAT1/miR-5582-3p/TCF7L2 axis might provide theoretical support for finding new diagnostic markers and therapeutic targets of breast cancer." (PMID 31300015, 2019). "Furthermore, other TCF7L2 SNPs besides rs4506565 are reported to be associated with increased risks of developing primary prostate, colon, and breast cancer." (PMID 28732081, 2017). "However, TCF7L2 has multiple polymorphic sites, and their associations with breast cancer are uncertain." (PMID 27738320, 2016). "In summary, we found that TCF7L2 SNPs (rs1225404 and rs7003146) might be associated with breast cancer risk in Northwest Chinese Han populations." (PMID 27738320, 2016). "However, several groups have made great efforts to explain the underlying effect of TCF7L2 in breast cancer." (PMID 27738320, 2016). "Further, SNPs in β-catenin rs4135385 was associated with increased risk (AG genotype; OR, 3.03) and TCF7L2 rs12255372 was associated with decreased risk of breast cancer (TT genotype; OR, 0.213) in older age group patients (>43 years) similar to that observed in the overall study population." (PMID 23516639, 2013). "Additionally, the TCF7L2 rs12255372 displayed significant association with decreased risk of breast cancer in ER- (OR, 0.105, CI, 0.013–0.853, p = 0.01351) category similar to that in the overall population but not in the ER + cohort." (PMID 23516639, 2013). "Additionally, the tag polymorphisms in TCF7L2 are associated with the clinical features of breast cancer, which may provide us novel insight into the pathogenesis of breast cancer." (PMID 27738320, 2016). "Further investigations on the interaction of EpCAM with SFRP1 and TCF7L2 and on additional factors, which may be causal for changes upon EpCAM overexpression, will help to characterize unique molecular properties of EpCAM-positive breast cancer cells." (PMID 21281469, 2011). "In breast cancer, we observed that the lead variants were significantly enriched in the TFs ESR1 (n = 73 genes), followed by TCF7L2 (n = 13) and FOXA1 (n = 11) (Fisher’s exact test, P < 0.01 for all)." (PMID 39535029, 2025). "mir-5582–3p was a unique suppressor miR that specifically targeted the TCF7L2 (transcription factor 7-like 2) gene to inhibit the stemness of breast cancer cells and breast CSCs." (PMID 39170516, 2024). "TCF7L2 has also been reported to be involved in the tumorgenesis of prostate cancer and breast cancer." (PMID 39060928, 2024).
breast cancer (continued). "IGFBP3 expression was down-regulated in Her2-positive breast cancer cells with trastuzumab resistance and led to the inhibition of the Wnt pathway and the rise of Cullin7 expression mediated by TCF7L2." (PMID 36660244, 2023). "Knockdown of circPRMT5 suppresses cell proliferation and angiogenesis and increases cell apoptosis in breast cancer while TCF7L2 overexpression reverses the antitumoral effects of circPRMT5 knockdown on breast cancer cell processes." (PMID 37042179, 2023). "TCF7L2 has been detected on the promoter of the cyclin D1 gene in human breast cancer cells, indicating that it increases cyclin D1 expression." (PMID 36476410, 2022). "TCF7L2 is a familiar oncogene overexpressed in breast cancer, nephroblastoma, and gastric cancer, but its role in OS remains unsure." (PMID 34753394, 2022). "LncRNA SPRY4-IT1 binds to miR-6882-3p by competing with TCF7L2 to affect the cell stemness of breast cancer." (PMID 34621314, 2021). "Of them, the top risk-associated TFs included well-known breast cancer master regulators, FOXA1, ESR1, and AR, and other related TFs, such as SIN3AK and TCF7l2." (PMID 34518541, 2021). "Taken together, these findings demonstrated that SPRY4‐IT1 promotes proliferation and stemness of breast cancer cells as well as renewal ability and stemness maintenance of BCSCs by increasing the expression of TCF7L2 through targeting miR‐6882‐3p." (PMID 31736268, 2020). "According to these results, we concluded that SPRY4‐IT1 promotes stemness of breast cancer cells and exerts its function through TCF7L2 in vivo." (PMID 31736268, 2020). "Dysregulation of Wnt/β-catenin pathway and TCF7L2 target genes play a role in carcinogenesis and is especially well documented for breast cancer." (PMID 31300015, 2019). "The cancer gene TCF7L2 is a component of the Wnt pathway, a recurrent fusion oncogene in human CRC, mutated in 14% of CRCs and breast cancers and a transposon target in murine genetic models of CRCs, liver tumors, and brain tumors." (PMID 29301589, 2018). "Previous studies have shown that TCF7L2 is highly expressed in hepatocellular carcinoma, breast cancer, esophageal squamous cell carcinoma, and other malignant tumors, and its expression correlates with their progress." (PMID 27738320, 2016). "A strong protective association was observed between SNPs rs7775 and rs12255372 in SFRP3 and TCF7L2, respectively with breast cancer." (PMID 23516639, 2013). "Except the SNP in β-catenin gene which was associated with increased risk of breast cancers, the other four SNPs in AXIN2, DKK3, SFRP3 and TCF7L2 genes were associated in a protective manner." (PMID 23516639, 2013). "Genotypic analysis of individual locus showed statistically significant association of five SNPs located in β-catenin, AXIN2, DKK3, SFRP3 and TCF7L2 with breast cancers." (PMID 23516639, 2013). "Our finding that TCF7L2 co-localizes and cooperates in gene regulation with a GATA factor in MCF7 breast cancer cells is similar to a recent study of TCF7L2 in hematopoietic cells." (PMID 22951069, 2012). "Probably, the reduction of both SFRP1 and TCF7L2 is required to more potently enhance Wnt signaling in breast cancer cell lines, and a contribution of additional factors cannot be excluded." (PMID 21281469, 2011). "Both low SFRP1 and TCF7L2 levels have been described in a subset of breast carcinomas derived from infiltrating ductal carcinoma." (PMID 21281469, 2011). "Therefore, TCF7L2 regulates breast cancer cell proliferation and stemness through the Wnt/β-catenin signaling pathway." (PMID 39170516, 2024). "The LUCAT1–miR-5582-3p–TCF7L2 axis increased the stem-like properties of breast cancer cells and stemness of breast cancer stem cells via the Wnt/β-catenin pathway, and LUCAT1 expression was related to tumor size, lymph node metastasis, TNM staging, and shorter OS in breast cancer." (PMID 36035299, 2022).
breast cancer (continued). "For example, increased 3-O-sulfation of heparan sulfate enhances expression of the Wnt-dependent transcription factor TFF4/TCF7L2 and 3D sphere formation in breast cancer cells and results in differential expression of constituents of the prognostically relevant hedgehog pathway." (PMID 35628603, 2022). "Likewise, the haplotype T-T in the TCF7L2 gene (rs7903146-rs12253372) was significantly related with breast cancer (OR = 2.66, 95%, CI = 1.64–4.30, p = 0.001)." (PMID 35996498, 2022). "The most recent breast cancer GWAS identified a 2–5 fold increased enrichment of risk SNVs in REs, mostly mapping to the binding sites for breast cancer–associated transcription factors including FOXA1, ESR1, GATA3, E2F1, and TCF7L2." (PMID 34439109, 2021). "Therefore, we revealed that miR‐6882 is a new tumour suppressor‐miR in breast cancer that inhibits stemness characteristics through directly targeting TCF7L2 and further affecting the Wnt/β‐catenin signalling pathway." (PMID 31736268, 2020). "Therefore, CCND1 is highly likely to be the gene that mediates rs614367 breast cancer susceptibility: variants in the enhancer region (either rs614367 or other functional variants) may be hypothesized to drive risk by disrupting E2F1/GATA3/MYC/TCF7L2/ZNF217 binding and affecting CCND1 expression." (PMID 30247654, 2019). "Interestingly, TCF7L2-regulated promoters are more enriched with well-known specific cancer initial development such as Epstein-Barr virus infection in breast cancer and metabolic in pancreatic cancer." (PMID 28499350, 2017). "Thus, our analysis suggest a statistically significant protection against breast cancer for women with TT genotype compared with the GG genotype in TCF7L2 gene (OR, 0.264; CI, 0.093–0.750; χ2 = 6.76, df = 1; p = 0.0093)." (PMID 23516639, 2013). "Finally, we showed that GATA3 (GATA binding protein 3), which co-localizes with TCF7L2 in MCF7 breast cancer cells, is required for recruitment of TCF7L2 to a subset of binding sites." (PMID 22951069, 2012). "Our studies show that TCF7L2 cooperates with the master regulator GATA3 to repress transcription in the well-differentiated MCF7 breast cancer cell line and suggest that a TCF7L2-GATA3 complex may be a critical regulator of breast cell differentiation." (PMID 22951069, 2012). "As Tcf7l2, Antxr1/Tem8, and Arhgap18 have been associated with human breast and other cancers, these data demonstrate that MMTV-induced insertional mutation remains an important means for identifying genes involved in breast cancer." (PMID 22087314, 2011). "With exception of VANGL2, up-regulation of the genes involved in Wnt signaling pathway, namely WNT5A, MSX2, TCF7L2 and TNFRSF11B, was confirmed in the validation set, further emphasizing the important role of the Wnt signaling pathway in PIK3CA-mutated breast cancer." (PMID 21209903, 2010). "Further experiments highlighted that SPRY4-IT1 may function as a ceRNA and sponge miRNA and thereby scaffolding target genes in cancers, such as miR-101-3p/EZH2 in cholangiocarcinoma, miR-101-3p/AMPK axis in gastric cancer, and miR-6882-3p/TCF7L2 in breast cancer cell stemness." (PMID 33204703, 2020). "In particular, TCF7L2 was shown to promote breast cancer cell invasion by upregulation of miR-21 and Wnt ligand induced β-catenin activation is also known to enhance invasion and metastasis of TNBC cells, suggesting the regulation of invasion could be mediated by modulating Wnt pathway in TNBC." (PMID 29179446, 2017). "Our results suggest that TCF7L2 polymorphisms rs1225404 and rs7003146, but not rs7903146, may affect breast cancer risk in Northwest Chinese women." (PMID 27738320, 2016). "Additionally, some but not all studies have linked polymorphisms in Tcf7l2 with increased breast cancer risk and more metastatic disease." (PMID 22087314, 2011).
breast cancer (continued). "Despite strong prior evidence that this SNP may play a role women's cancer susceptibility, we conclude that variation in TCF7L2 is not likely to be associated with risk of non-familial breast cancer or ovarian cancer." (PMID 19732438, 2009). "As a miR-5582–3p sponge, LUCAT1 targeted TCF7L2, activated the Wnt/β-catenin pathway, and promoted breast CSC self-renewal and breast cancer cell growth." (PMID 39170516, 2024). "On the other hand, TCF7L2, ARRB1, DLL1, FZD7, HES1, and JAG1 transcript levels were significantly lower in breast cancer tissues than in normal samples (p < 0.0009, p = 0.0131, p = < 0.0001, p = < 0.0001, p = 0.0138, and p < 0.0001, respectively)." (PMID 36476410, 2022). "Further studies revealed that LUCAT1 increased stem-like properties of breast cancer stem cell, and lncRNA LUCAT1/miR-5582-3p/TCF7L2 axis modulated breast cancer stemness via Wnt/β-catenin pathway." (PMID 34345203, 2021). "Our data show that SID peptide downregulates Wnt/β-catenin reporter activity and direct Wnt target genes (LEF1, TCF7L2, CD44, PLAU, MT1-MMP, MMP9, HMGA2) involved in breast cancer invasion and metastasis." (PMID 29179446, 2017). "Here, we used a high throughput approach to identify additional CISs in MMTV-induced mammary tumors and found several novel MMTV target genes including Arhgap18, Tcf7l2, Prkaca and Antxr1/Tem8 (called Antxr1 from here-on)." (PMID 22087314, 2011). "The transcriptionally competent β-catenin/TCF7L2 complexes provoke an excessive expression of TCF7L2 target genes, such as the cyclin D and c-MYC oncogenes, which is a common feature in human cancers, including breast cancer (BC)." (PMID 17109766, 2006). "Specifically, we show that TCF7L2 has highly cell type-specific binding patterns, co-localizes with different factors in different cell types, and can be tethered to the DNA by GATA3 in breast cancer cells." (PMID 22951069, 2012). "We also examined the expression of these genes in a separate cohort of 698 luminal (ER/PR+) breast cancers using the TCGA dataset, where PIK3CA-mutant cancers displayed significantly higher expression of eight Wnt genes (LEF1, TCF7L1, TCF7L2, CTNNB1, LRP6, SFRP2, WNT5A, and MSX2)." (PMID 34035258, 2021). "For example, a GATA3 motif was identified through analysis of TCF7L2 ChIP-seq peaks from breast cancer cells; follow-up studies demonstrated that GATA3 and TCF7L2 interact with each other and that depletion of GATA3 in breast cancer cells reduces binding of TCF7L2 to specific sites." (PMID 30866492, 2019).
Insulin resistance (55 papers, 2009 to 2026). Increased resistance towards insulin, that is, diminished effectiveness of insulin in reducing blood glucose levels. "In the current systematic review, observational studies showed that TCF7L2 modified the association between the diet (including dietary and serum fatty acids and fiber) and insulin resistance." (PMID 36155628, 2022). "Fatty acids induce insulin resistance, and this effect was more pronounced in TCF7L2 risk-allele carriers." (PMID 36155628, 2022). "Association of the risk allele of TCF7L2 gene with insulin resistance and post meal insulin resistance has been reported before." (PMID 36263318, 2022). "Following bed rest, the participants with the TCF7L2 rs7903146 risk variants also fail to show an incremental rise of FPIR in response to insulin resistance." (PMID 35477971, 2022). "Regarding artichoke extract supplementation (ALE), two RCTs observed that ALE supplementation significantly decreased insulin concentration and improved insulin resistance in the TT genotype of the rs7903146 variant of TCF7L2." (PMID 36155628, 2022). "Disturbances in insulin sensitivity and induction of insulin resistance are among the molecular mechanisms through which TCF7L2 rs7903146 variant increases the risk of T2DM." (PMID 35585604, 2022). "This association with T2DM independently of BMI, insulin resistance and other metabolic indices confirms that impaired insulin secretion is a result of genetic defect of TCF7L2." (PMID 34073870, 2021). "The TCF7L2 gene was reported to be associated with T2D, insulin sensitivity, and insulin resistance." (PMID 29871606, 2018). "The T allele of TCF7L2 rs7903146 polymorphism was associated with a reduced compensation of insulin secretion for insulin resistance induced by 9 days of bed rest." (PMID 27058589, 2016). "Our results demonstrated that TCF7L2 rs290487, rs6585194 and rs7094463 polymorphisms were correlated with insulin resistance and insulin secretion of patients with GDM." (PMID 27465520, 2016). "The manual disease annotations for Foxo1 point to both T1D and T2D associations, as well as insulin resistance, heart failure, premature aging and, like TCF7L2, to pancreatic neoplasms." (PMID 27602200, 2016). "Whether TCF7L2 gene associated postprandial lipid dysmetabolism leads to insulin resistance or TCF7L2 associated insulin resistance results is postprandial lipid dysmetabolism cannot be said with certainty from the current study." (PMID 36263318, 2022). "It is very well possible that in Caucasians, who have a much higher subcutaneous fat depot (SAT) and an abundance of mature adipocytes, it is the down regulation of TCF7L2 gene in mature adipocytes that plays a dominant role in causing insulin resistance and glucose intolerance." (PMID 36263318, 2022). "Taken together, our findings with respect to rs7903146 polymorphism indicate that postprandial dysmetabolism could be an important contributor to TCF7L2 associated insulin resistance." (PMID 36263318, 2022). "Insulin resistance to artichoke leaf extract (ALE) may be affected by TCF7L2-rs7903146 polymorphism." (PMID 33126534, 2020). "Furthermore, the TCF7L2 gene plays an important role in regulating adipose tissue development and function, and this is probably associated with the increase in insulin resistance." (PMID 31083695, 2019). "Specifically, collider stratification may bias the TCF7L2-BMI association downwards when the ratio T2D cases to controls has been distorted to over-represent cases, or cases with more favorable insulin resistance profiles." (PMID 30305909, 2018). "The association of TCF7L2 genetic variant with increased insulin resistance and decreased insulin secretion may help understand GDM pathogenesis." (PMID 27465520, 2016). "In line with this, a conditional deletion of Tcf7l2 in adipocytes in mice exposed to HFD leads to insulin resistance and adipocyte hypertrophy, enhanced weight gain, and an impaired glucose and lipid metabolism." (PMID 41614817, 2025).